IFNG (interferon gamma)
Diseases named in the same sentence as IFNG in open-access papers (continued):
Sharing a sentence is not in itself a finding about the gene and the disease.
melanoma (continued). "Moreover, scRNA-seq analysis revealed pervasive IFNγ signaling in both myeloid and melanoma cells of B16F10 tumors." (PMID 37996514, 2024). "Moreover, we found significant enrichment of pro-inflammatory IL6, TNF, and IFNγ gene sets in macrophages that had taken up melanosomes secreted by MNT1 melanoma cells and in those that had taken up melanosomes from either keratinocytes or fibroblasts." (PMID 38719996, 2024). "To further characterize the effect of MITF knockdown and IFNγ treatment on the differentiation status of 624Mel cells, we performed GSEA using established gene sets that specifically associate with differentiation stages in melanoma cells." (PMID 39736644, 2024). "In sum, our findings support the hypothesis that GRASLND inhibits IFNγ signaling in melanoma, suggesting an immune evasion mechanism of melanoma cells by upregulating lncRNA GRASLND." (PMID 39398277, 2024). "IFNγ alone reduced cell viability to 40%, aligning with the known effect of IFNγ on melanoma cells." (PMID 39237877, 2024). "Finally, to explore potential direct effects of IFNγ on B16F10 melanoma cells, we generated Ifngr1-knockout B16F10 cells." (PMID 37996514, 2024). "Furthermore, we show that IFNγ stimulated dedifferentiated melanoma cells display increased secretion of CCL2, IL-10, CXCL10 and PD-L1 and increased PD-L1 expression on their cell membranes." (PMID 39736644, 2024). "To get a first impression of the applicability, accuracy and reproducibility of pulsed SILAC (pSILAC) for quantitative immunopeptidomics, we performed a proof-of-concept experiment to monitor the modulation of the immunopeptidome of a melanoma cell line by IFNγ." (PMID 39835134, 2024). "Dedifferentiation renders 624Mel melanoma cells hypersensitive to IFNγ stimulation in a context-dependent manner, resulting in non-additive upregulation of IFNγ-induced genes, increased PD-L1 protein expression and amplified secretion of CCL2, CXCL10 and IL-10." (PMID 39736644, 2024). "However, to our knowledge, this is the first study to directly link MITF expression alone with the IFNγ response in melanoma cells." (PMID 39736644, 2024). "Finally, PD-L1 and MHC-I were also induced at the cell surface of TH1902-treated B16-F10 melanoma cells, both of which were also induced by interferon gamma." (PMID 38482021, 2024). "Importantly, IFNγ is known to induce PD-L1 expression in melanoma cells through the JAK1/2-STAT1/3-IRF1 axis, and there are indications that some melanoma cell lines display increased IFNγ-induced PD-L1 expression when dedifferentiated." (PMID 39736644, 2024). "Interferon-γ (IFNγ) is an integral part of the anti-tumor immune response and can directly induce both differentiational changes and expression of immunosuppressive proteins in melanoma cells." (PMID 39736644, 2024). "Similarly, interferon-γ (IFNγ) stimulation has been shown to induce dedifferentiation in melanoma cells." (PMID 39736644, 2024). "Indeed, we identified increased IRF1 and CD274 mRNA levels after exposure of melanoma cells to IFNγ, correlating with increased membrane PD-L1." (PMID 39237877, 2024). "Mutations in JAK/STAT pathway components could similarly affect the interplay between IFNγ signaling and dedifferentiation, as they can affect the general responsiveness of melanoma cells to IFNγ." (PMID 39736644, 2024). "In addition, it is also called melanoma differentiation-associated gene-9 (MDA-9) because it has been confirmed that syntenin expression is regulated by the treatment of mezerein and interferon-gamma in human melanoma cells." (PMID 37298370, 2023). "In this regard, pro-inflammatory cytokines such as interferon gamma (IFNγ) or other signals may be being released by the melanoma cells which may function to activate memory T cell responses." (PMID 37156818, 2023).
melanoma (continued). "Additionally, IFNγ and IFNγΔKRKR induced upregulation of H-2Kb/H-2Db molecules on B16-F10 melanoma cells in a similar and concentration-dependent manner." (PMID 36732425, 2023). "Alternatively, NK cells might eliminate melanoma cells through the secretion of TNFα and IFNγ promoting Th1 differentiation and the recruitment of CD8+ T cells into regressing tumors." (PMID 37526660, 2023). "Having established that Ptpn2 gene knockout sensitizes melanoma cells to IFNγ treatment, we next asked whether the small-molecule Ptpn2 inhibitors (PTP 1 through PTP 10) could have the same effect." (PMID 36968224, 2023). "Importantly, the enforced inability of (patient-derived) melanoma cells to downregulate MITF diminished their sensitivity to IFNγ." (PMID 36812891, 2023). "Therefore, we utilize data from Matshushita and coworkers where they explicitly explored the antiproliferative effects of IFNG following in vivo T cell adoptive transfer by means of a cell cycle sensor in B16F10 melanoma." (PMID 37182110, 2023). "In line with these metabolic changes, PD-1-deficient Tbet+NK1.1− ILCs expressed significantly increased IFNγ and granzyme B and K. Furthermore, PD-1-deficient Tbet+NK1.1− ILCs contributed toward diminished tumor growth in an experimental murine model of melanoma." (PMID 37098069, 2023). "Losses and mutations in these genes have been linked to primary and acquired resistance to PD-1 blockade in melanoma, suggesting that melanoma cells become insensitive to the antiproliferative effects of IFNγ (via JAK1/2 alterations) or lose antigen presentation (via B2M alterations)." (PMID 36977461, 2023). "We examined IFNγ signaling in PD1 PROG melanoma cells treated with 1000 U/ml IFNγ for 24 h." (PMID 36934113, 2023). "In this study, we take a systems biology approach to compare the importance of cytolytic versus IFNG-mediated cytostatic effects in a murine melanoma model (B16F10) and to dissect the contribution of immune checkpoints HAVCR2, LAG3, and PDCD1/CD274 to CTL exhaustion." (PMID 37182110, 2023). "Altogether, we conclude that IFNγ-inducible NAMPT is an important player in melanoma cell growth." (PMID 36900204, 2023). "However, treatment with IFNγ can induce MHC class I expression on B16 melanoma cells, as shown here and by others." (PMID 36546872, 2023). "Transgenic CD8+ T cells expressing the 11Cαβ- or 2Cαβ-cTCR elicited IFNγ spot formation above background levels when co-cultured with the endogenously HLA-C*07:01+ melanoma cell lines D10, D41, the glioblastoma cell line MZ-257-GBM/HLA-C*07:01 and the lung cancer cell line MZ-LC-16/HLA-C*07:01." (PMID 37849763, 2023). "Melanoma patients with high expression of IFNG and DAPK2 have a better prognosis." (PMID 36690663, 2023). "Furthermore, elevated IFNγ signalling is observed in a significant proportion of melanoma and NSCLC lesions that progress on ICBT7,8." (PMID 37752135, 2023). "Therefore, we stimulated B16 melanoma cells with IFNγ for 24 hours to upregulate MHC class I expression." (PMID 36546872, 2023). "We observe upregulation of poly-ADP ribosyl polymerase 14 (PARP14) in chronic IFNγ-treated cancer cell models, in patient melanoma with elevated IFNG expression, and in melanoma cell cultures from ICBT-progressing lesions characterised by elevated IFNγ signalling." (PMID 37752135, 2023). "To investigate this, we co-treated melanoma cells with IFNγ and epacadostat." (PMID 36812891, 2023). "A mechanistic study in the B16 melanoma model demonstrated that IFNγ-driven resistance mechanisms may be due to signaling effects on tumor cells, and disruption of tumor-specific IFNγ signaling can rescue ICI sensitivity." (PMID 38130991, 2023). "In a recent clinical trial, patients with stage IIIB, IIIC or IV melanoma received an intratumoral IFNγ injection after they received a vaccine containing 12 class I major histocompatibility complex-restricted melanoma peptides that increased vaccine-induced tumor-infiltrating lymphocytes." (PMID 38006049, 2023).
melanoma (continued). "Interferon gamma (IFNγ) ELIspot data showed that more patients developed a T cell response to virus encoded TYRP1 at higher DLs, and a subset of patients also had a response to other melanoma antigens, including gp100, suggesting epitope spreading." (PMID 38022659, 2023). "Injection of recombinant IFNγ was tried in several anti-tumor clinical trials including chronic myelogenous leukemia, bladder carcinoma, ovarian cancer, adult T cell leukemia and melanoma, but the results were mixed." (PMID 38020179, 2023). "The expression of IFNγ in these two tumors leads to melanomas becoming resistant to immunotherapy." (PMID 37174106, 2023). "Notably, the “Hallmark Interferon Gamma Response” and “Hallmark TNFA Signaling via NFKB” gene signatures correlated with KEAP1 expression in melanoma CTCs and in tumor samples and cell lines from the Cancer Genome Atlas (TCGA)." (PMID 36864091, 2023). "The high transcriptional IL4I1 expression by MHCII+ CD163− TAMs in MeLiM pigs with regressing melanoma was unexpected, but may result from the enriched IFNγ, TNFα, IL12 and IL6 tumor microenvironment between R0 and R1 stages." (PMID 37526660, 2023). "After observing the IFN induction of NAMPT expression in melanoma cells, we investigated whether IFNγ-inducible NAMPT promoted proliferation in vitro." (PMID 36900204, 2023). "Here, we confirmed that interferon-gamma (IFN-γ)-induced PD-L1 expression in melanoma cell lines." (PMID 37444518, 2023). "Furthermore, SCNAs in IFNG, the gene encoding IFN-γ, were also found to be enriched in ICI-resistant patients with melanoma." (PMID 35703181, 2022). "Interestingly, delivery of miR-21-3p to melanoma cell lines was found to promote interferon-gamma (IFN-γ)-mediated ferroptosis by targeting thioredoxin reductase 1 and elevating ROS generation." (PMID 36139366, 2022). "Interestingly, tissular diffusion of IFNγ was recently addressed with melanoma cells as the penetrance of the cytokine was dependent on the density of cytokine-consuming cells in the tissue, creating a gradient of concentration." (PMID 36611907, 2022). "The main inducer of PD-L1 expression in melanoma is therefore IFNγ." (PMID 34268602, 2022). "Knockdown of FTO could sensitize melanoma cells to interferon gamma and anti-PD-1 treatment in mice." (PMID 35371987, 2022). "For example, key cytotoxic molecules, granzyme B and perforin as well as Interferon gamma (IFNg) production were reduced in SRC-3–deficient NK cells and in-vivo tumor surveillance of these cells was impaired as demonstrated using B16F10 mice melanoma model." (PMID 36582250, 2022). "Interferon-gamma (IFN-γ) is shown to stimulate melanoma development and progression." (PMID 35105915, 2022). "Even though the samples were from different tissues (colorectal versus melanoma) and the experiments were set up differently (proteomics versus peptidomics), the same W>F substitutant was observed in the proteomics analysis of melanoma MD55A3 cells after IFNγ treatment (QYKIPDfFLNR)." (PMID 35264796, 2022). "Additionally, FTO depletion sensitizes melanoma cells to interferon-gamma (IFNγ) and sensitizes melanoma to anti-PD-1 treatment." (PMID 35186927, 2022). "Human melanomas harbor IFNγ-producing macrophages in the tumor microenvironment." (PMID 34385592, 2022). "However, both the RNAseq data and the in vitro data indicate a secondary role for hypoxia/HIF1 in the regulation of PD-L1 expression in melanoma compared to the IFNγ/JAK/STAT pathway, the key regulator of PD-L1 expression." (PMID 34268602, 2022). "In addition, genetic alterations which interfere with the interferon-gamma (IFN-γ) signaling pathway are also known to affect the antitumor responses in melanoma patients treated with immunotherapy." (PMID 36463238, 2022). "Indeed, at concentrations where wildtype melanoma cells were barely affected by IFNγ or T cell attack, STUB1-deficient melanoma cells were eliminated efficiently." (PMID 35395848, 2022).
melanoma (continued). "Motivated by these observations, we hypothesized that mutations in the IFNγ pathway could also affect immunogenicity in melanoma patients, apart from the high IFNγ levels." (PMID 36389735, 2022). "Moreover, knockdown of alpha-ketoglutarate-dependent dioxygenase (FTO) in tumor cells sensitized to interferon gamma (IFN-γ) in vitro enhances the PD-1 treatment in murine melanoma." (PMID 35677634, 2022). "Importantly, in the correlation analyses in human cancer patients by data mining of TCGA database, there were positive correlations among CD11C, CD274, CSF1R, and IFNG expression in lung adenocarcinoma, lung squamous carcinoma, and melanoma." (PMID 35917184, 2022). "In this same study, B16 melanoma cells increased MHC-II expression in vivo in an IFNγ-dependent manner, and the adoptively transferred CD4+ T cells could kill tumor cells in vitro and reject challenge tumors in vivo in an MHC-II-dependent manner." (PMID 36159781, 2022). "Aberrant CIITA expression in melanomas results from the activation of both IFNγ-inducible and constitutive CIITA promoters, and deletion of the same AP-1 site that we found differentially occupied by Jun in Fbw7 mutant Hct116 cells compromised CIITA expression in melanoma cells." (PMID 35225231, 2022). "IFNG predicted survival and the response to ICIs in melanoma." (PMID 35373463, 2022). "Elevated IL2RA, IL2RG, IL7R, and IFNG expression may play a central role in promoting melanoma metastasis through up regulation of intratumoral regulatory T—cell proportion mainly by activation of JAK—STAT signaling pathway." (PMID 34159752, 2021). "In addition, Socs2 is upregulated by interferon-gamma (IFNγ) in DCs in human melanoma, and Socs2−/− mice exhibit enhanced DC priming of Tcell responses to give improved antitumor immunity." (PMID 34857742, 2021). "Therefore, FTO depletion sensitizes melanoma cells to interferon gamma (IFNγ) and anti-PD-1 treatment in mice." (PMID 33611339, 2021). "Moreover, bromodomain-containing 4 (BRD4) was rapidly recruited to the PD-L1 locus, accompanied by increased H3K27ac and RNA Polymerase II (RNA Pol II) occupancy in melanoma cells after IFNγ stimulation." (PMID 34365463, 2021). "In human melanoma, colon cancer, breast cancer, and other cancer types, IL-32 can be induced by tumor necrosis factor (TNFα and IFNγ to inhibit cancer development, and its high expression may be related to the therapeutic effect of PD1." (PMID 34414188, 2021). "IFNG was another key gene identified to correlate with poor outcomes in melanoma in our study." (PMID 34159752, 2021). "Hence, the efficacy of vaccines to best control multifocal disease in our melanoma models appears to be associated with the development of broadly reactive CD8+ T cell responses and enhanced IFNγ+CD8+ TIL survival." (PMID 33408093, 2021). "Here, we explored that interleukin 17 (IL-17) cooperating with IFNγ transforms BMSCs into TA-MSCs, which promotes tumor progression by recruiting macrophages/monocytes and myeloid-derived suppressor cells (MDSCs) in murine melanoma." (PMID 33889575, 2021). "The CD40KD melanoma cells were resistant to IFNγ-mediated induction of CD40 expression." (PMID 34092233, 2021). "IFNG expression has been found to be a predictive marker of sensitivity to immune checkpoint inhibitors nivolumab and pembrolizumab in non-small cell lung cancer and melanoma cases, respectively." (PMID 33803939, 2021). "We have previously shown that a cytokine cocktail consisting of IL‐1β, TNFα, IFNγ, IFNα, and Poly I:C can yield stable, type‐1 polarized DC that produce up to 100‐fold higher levels of IL‐12p70 and can induce very high levels of melanoma‐specific CTLs as compared to standard DCs." (PMID 32663904, 2021). "Overexpressed IL2RA, IL2RG, IFNG, and IL7R were identified as the hub genes associated with melanoma metastasis, and may promote melanoma progression through activation of JAK—STAT signaling pathway." (PMID 34159752, 2021).